TNF (tumor necrosis factor)
Diseases named in the same sentence as TNF in open-access papers (continued):
Sharing a sentence is not in itself a finding about the gene and the disease.
breast carcinoma (continued). "To understand better the mechanism by which TNFα increases PTX3 production in breast cancer cells, we examined the effects of inhibitors of extracellular signal-regulated protein kinase (ERK), p38 mitogen-activated protein kinase (MAPK), JNK, or NF-κB on PTX3 expression." (PMID 24457902, 2014). "Interestingly, analogous to T.annulata infected macrophages, MDA-MB231 breast cancer cells showedsignificantly increased motile and invasive properties when stimulated with TNFα." (PMID 28357238, 2014). "Breast cancer epithelial cells produce large amounts of TNF, which through binding to TNF receptor I inhibits the differentiation of fibroblasts and preadipocytes into mature adipocytes, providing a molecular basis for the desmoplastic reaction commonly seen in breast cancer." (PMID 25505738, 2014). "Moreover, Ke Su's study identified that a decrease of VASP mRNA and protein expression mediated the TNF-α-induced adhesion and proliferation inhibition of breast cancer MCF-7 cells." (PMID 25051011, 2014). "We analyzed not only the association of individual polymorphisms and breast cancer risk, but also the effects of combinations of functionally related polymorphisms (NFKB1 and NFKBIA; IL-8 and IL-10; and TNF c.-418 and c.-488), menopausal status, histopathological type, and cancer grading." (PMID 25559835, 2014). "Furthermore, we found that the effects of 25OHD and TNFα on breast cancer ER status were independent from each other." (PMID 24473087, 2014). "Similar findings were shown in TNF-α-induced breast cancer associated EMT and metastasis, where those processes were reliant on NF-κB-dependent Snail stabilization; such stromal activation is a key feature of breast cancer progression." (PMID 24811539, 2014). "It has been proposed that these natural products could enhance the sensitivity of human breast cancer cells to TNF-α by disturbing the balance between complex I and complex II." (PMID 25419573, 2014). "Furthermore, increased inhibition of XIAP resulting in apoptosis was observed in these breast cancer cells when treated with a combination of TNF-α and WA or Cel." (PMID 25419573, 2014). "On the other hand, IL8 variant genotype and heterozygous genotypes of both TNF polymorphisms were associated with decreased risk of IDC but not of other types of breast cancer." (PMID 25559835, 2014). "To better understand the roles of single nucleotide polymorphisms (SNPs) in the TNF-α, TNFRSF1A and TNFRSF1B genes in the development of breast cancer, we explored the associations between SNPs in these three genes and breast cancer susceptibility in northeast Chinese Han women." (PMID 25010932, 2014). "The outcome of such a process, if taking place in vivo in malignancies with high TNFα expression - as is the case in breast cancer - may be high production of pro-tumorigenic factors by the tumor cells, including angiogenic ones (such as CXCL8 and CCL2)." (PMID 24598028, 2014). "Moreover, it has been observed that breast cancer patients with elevated levels of TNF-α in the circulation have a poor prognosis." (PMID 25010932, 2014). "We further examined the antioxidant potential (ORAC assay) of the extracts, their ability to influence viability of prostate cancer (PC-3) and breast cancer (MCF-7) cells as well as their lowering effect on TNF- α-induced adhesion molecule expression in endothelial cells (HAEC)." (PMID 24752205, 2014). "Similarly to the case of TNFα, we also found synergistic associations between 25OHD and IL5 on breast cancer ER status in premenopausal patients." (PMID 24473087, 2014). "NFKB1 c.-798_-795delATTG ins/del and del/del genotypes, and IL-10 c.-854 TT genotype were associated with increased breast cancer risk, while IL8 c.-352 TT genotype, TNF c.-418 GA and AA genotypes, and c.-488 GA genotype were significantly associated with a reduced risk." (PMID 25559835, 2014). "TNFα can also up-regulate Slug, which imparts breast cancer cells with a stem cell-like phenotype." (PMID 23431386, 2013).
breast carcinoma (continued). "We investigated the possibility that the thioredoxin system protects against TNF-α-induced cancer cell death by examining whether TR1/Trx1 status controls TNF-α-induced apoptosis in EMT6 murine breast cancer cells." (PMID 24039713, 2013). "This is particularly evident following the recent publication by Mahul-Mellier on Hela and MCF7 breast cancer cells, where downregulation of USP2a by siRNA promotes NF-kB activation and protects cells against TNF-induced cell death, as a consequence of the impairment of the USP2a-TRAF protein ratio." (PMID 24071644, 2013). "Therefore, we suggest considering the addition of these established TNFα inhibitors to the treatment protocols of luminal breast cancer patients." (PMID 24369447, 2013). "Taken together, these observations suggest that a relatively high subpopulation of luminal breast cancer patients may experience coexposure to TNFα + Estrogen + EGF and may thus acquire increased metastatic rate." (PMID 24369447, 2013). "We hypothesized that human plasma, tumor spheroid culture, and exposure to pro-inflammatory cytokines such as IL-6 and TNF-α could induce robust interactions between metastatic breast cancer cells in circulation and the inflamed endothelium." (PMID 23372803, 2013). "Thus, TNF-α-stimulated breast cancer cells that have lost TR1 or Trx1 showed specific localization of p-ERK 1/2 to the nucleus in association with apoptosis." (PMID 24039713, 2013). "A recent study showed that TNFα induces EMT via up-regulation of Twist in breast cancer cells." (PMID 23431386, 2013). "Thus, our data indicate that SLC inhibits TNFα-induced highly metastatic MDA-MB-231 human breast cancer cell migration, invasion, and NF-κB activation." (PMID 23997800, 2013). "Breast cancer survivors with persistent and gradually aggravating fatigue after treatment had increased levels of immune markers related with proinflammatory cytokine such as interleukin (IL-6) and tumor necrosis factor (TNF-α) activity." (PMID 22203880, 2012). "Other work has found that TNF-alpha is an important factor in breast cancer promotion and survival." (PMID 22536907, 2012). "Consistently, high levels serum TNF-α positively correlate with high tumor grade in breast cancer." (PMID 22529912, 2012). "At the same time, more and more studies connect TNF-α expression in triple negative breast cancer with the blockage of estrogen and progesterone receptors, increasing the poor prognosis of the patients with this subtype of breast cancer." (PMID 23263670, 2012). "Using other NF-κB activating agents such as TNF and surveying more extensive NF-κB-target gene sets may help to refine the ING4/NF-κB gene signature associated with aggressive breast cancer." (PMID 23056468, 2012). "Additionally, inhibition of TNFα has been shown to decrease breast cancer cell aggressive behavior, including metastasizing to bone." (PMID 22731827, 2012). "TNF-α blocked growth of breast cancer cells by impairing IGF-IR signaling." (PMID 22235273, 2012). "The ROS generated by the presence of slaked lime in BQ may amplify AKR1B1 gene rendering TNFα induced proliferation of breast cancer cells." (PMID 22937096, 2012). "Therefore, we decided to test the effects of combined treatment of anti-HER2 antibody BH1 and TNF-α on four breast cancer cell lines using a checkerboard assay." (PMID 23033967, 2012). "One of the important observations in our study was the recognition of inflammation related factors in the IPA network and a number of pathway showed IL-5, IL-1β, TNF, IL-4, and INFγ as the central molecules highlighting an already existing relationship between inflammation and breast cancer." (PMID 23216862, 2012).
breast carcinoma (continued). "TNFα has been shown to induce TRAIL expression in breast cancer cells." (PMID 21264227, 2011). "However, in terminal cancer patients, TNF-α is also implicated in cachexia, a loss of adipose and skeletal muscle mass, and accordingly elevated TNF-α in the serum of lymphoma and breast cancer patients was correlated with poor survival." (PMID 24212939, 2011). "The TNF secreted by tumor-related macrophages can enhance the invasion of tumors by increasing the expression of matrix metalloproteases (MMPs) in breast carcinoma and vascular endothelial growth factor (VEGF) in the c-Jun N-terminal kinase (JNK) and the NF-KB signaling pathways." (PMID 21345194, 2011). "The growth inhibition of human breast carcinoma cells and tumors could be related to the concomitant down-regulation of IL-6, IL-8, and TNF-α in breast carcinoma cells by these drugs." (PMID 21345194, 2011). "Blocking experiments with HPA showed that adhesion of breast cancer cells with HPA-positive glycotopes to TNFα-activated endothelial cells could be blocked by HPA, whereas this was not the case with HPA-negative breast cancer cells." (PMID 20010946, 2010). "The hypothesis is also supported by an increased expression of the anti-apoptotic genes BCL2, TNF and transcriptional factor NF-kappaB which protects breast cancer cells from apoptosis." (PMID 20723247, 2010). "Cisplatin injection increased TNF-α in serum on 5th day as compared to breast cancer control group." (PMID 19356226, 2009). "With the combination of 2-DE and western blot techniques and the aid of tunicamycin, we analyzed N-glycosylation variants of VCAM-1 in primary human endothelial cells stimulated with either TNF or tumoral soluble factors (TSF's) derived from the human breast cancer cell line ZR75.30." (PMID 19930605, 2009). "Breast cancer invasion has previously been shown to be strongly promoted by TNFα, and in our experiments IL-17-dependent invasion was of similar magnitude to that achieved following stimulation with TNFα." (PMID 19014637, 2008). "Less well characterized is the role of lipid metabolism (cluster 79) and immunological aspects in the differential response to tamoxifen (clusters 784, 375) though TNF alpha and TGF beta have previously been implicated in breast cancer development and progression." (PMID 18498629, 2008). "The arising question, in view of our data, is which might be the functional role of the TNF-related system of BAFF-APRIL in breast cancer." (PMID 18366696, 2008). "We examined the effect of PrP expression on the viability of MCF-7 breast carcinoma cells treated with TNF-α, HpL3-4 immortalized hippocampal neurons deprived of serum, and cultured cerebellar granule neurons induced to undergo two kinds of Bax-dependent apoptosis." (PMID 18718018, 2008). "Recent studies have shown that Ganoderma lucidum can induce apoptosis of prostate cancer cells (PC-3) via decreasing the expression of NFKB1-regulated genes and Ganoderma lucidum is able to inhibit TNF-induced proliferation of human breast cancer cells through modulation of the NFKB1 signaling." (PMID 18854039, 2008). "By assessing migration of various breast cancer cells across TNF-α pre-activated human umbilical vein endothelial cells (HUVECs), we found that breast cancer cells migrated across HUVEC monolayers differentially and that transmigration was E-selectin dependent." (PMID 18350162, 2008). "We therefore investigated the possibility that IL-17 exerted its effect on breast cancer cells by inducing TNFα secretion, which in turn could drive MMP-dependent tumour invasion." (PMID 19014637, 2008). "Notably, EOGT expression was upregulated in the TNFα-treated mouse breast cancer cell line 4T1." (PMID 40299340, 2025).
breast carcinoma (continued). "For instance, Leptin and Insulin levels decreased, particularly in Breast cancer patients, whereas Colorectal cancer patients exhibited a reduction in pro-inflammatory cytokines such as IL-1β, IL-6, IL-8, and TNF-α, even in the absence of weight loss and bioimpedential feature changes." (PMID 41409302, 2025). "Therefore, we cannot exclude the possibility that OVOL2 may affect lipid catabolism in breast cancer cells by modulating the activity of the TNF pathway." (PMID 38627980, 2024). "Activation of TNF-α and IL-1β in breast cancer can lead to abnormal genetic transcription, which is beneficial to cancer cells and aids in their resistance to apoptosis, making Nf-κB a critical target in breast cancer therapeutics, particularly in the more aggressive subtypes." (PMID 39728433, 2024). "Therefore, we combined PARP1, p50 and TNF-α to detect breast cancer prognosis." (PMID 38388665, 2024). "Ascites proinflammatory cytokines IL-1β, IL-6, TNF-α were increased in model mice, but were significantly reduced following EFL1 or DOX administration, which demonstrates that EFL1 is able to decrease the generation of proinflammatory cytokines caused by breast cancer liver metastasis." (PMID 37709489, 2023). "The importance of HIIT for breast cancer patients may stem in part from its anti‐inflammatory mechanisms, achieved through the down‐regulation of pro‐inflammatory factors such as IL‐6, and the up‐regulation of anti‐inflammatory factors like IL‐10 and TNF‐α." (PMID 37587859, 2023). "TAMs can play a role in endocrine resistance; for example, macrophages may induce endocrine resistance in ER+ breast cancer cells by inducing sustained release of TNF-α and IL-6 from breast cancer cells, resulting in activation of NFκB, STAT3, and ERK-1 and hyperphosphorylation of ERα." (PMID 36909339, 2023). "Therefore, TNF-α blockers combined with cancer therapies may be beneficial in the treatment of patients with CD and breast cancer." (PMID 37138170, 2023). "MDD is associated with higher circulating levels of inflammatory cytokines, such as interleukin (IL)‐6, IL‐8, IL‐1β, TNF‐α, soluble IL‐2 receptor (sIL‐2R), and C‐reactive protein (CRP), which promote cellular proliferation in breast tissue and have also been linked to development of breast cancer." (PMID 35852181, 2023). "Thus, compound 30 could be considered a potential anti-breast cancer lead molecule, possibly by targeting TNFα." (PMID 37745072, 2023). "It showed that CCMNBs can break through the limitation of universal cancer biomarker recognition, make tumor necrosis factor biomarker targeting not affected by the high heterogeneity of breast cancer tissue, and thus improve the diagnostic ability and potential drug targeting delivery ability." (PMID 37781205, 2023). "The present results suggest that breast cancer survivors with PD have worse cognitive functioning based on a cognitive screening test and lower quality of life than the PD group, and significantly higher levels of IL‐1β, TNF‐α, and IL‐4, compared to the patients with NPD." (PMID 36965094, 2023). "Furthermore, NDR1 might function as a hub to modulate IL-6, TNF-α or Wnt3a induced activation of Notch1 signaling pathway and enrichment of breast cancer stem cells." (PMID 35508987, 2022). "Thus, among the pro-inflammatory cytokines in breast cancer, the content of IL-1β, IL-2, and IL-6 increased (+16.1%, +25.0%, and +12.7%, respectively), while for TNF-α, MCP-1, IL-8, and IL-18, the content decreased (−36.2%, −23.8%, −15.0%, and −12.1%, respectively)." (PMID 36286034, 2022). "Costantini and colleagues reported that a hydrophilic fraction of the oil from pomegranate [(Punica granatum L. (Lythraceae)] seeds caused a decrease in viability and TNF-α concentration in breast cancer cell lines, but no significant impact on apoptosis was discovered." (PMID 36232888, 2022).
breast carcinoma (continued). "Among the important factors for the progression of breast cancer, TNFα plays an essential role in promoting the growth of the tumor and metastasis; so that it is proven that anti-TNFα antibodies can prevent the proliferation of breast cancer cells and metastasis." (PMID 35933373, 2022). "Thus, we initially examined that whether NCOR1 expression is specifically regulated by TNFα in MCF7 ERα-positive breast cancer cells." (PMID 34073371, 2021). "In breast cancer, it was reported that the TNFα -308 G>A allele is associated with higher expression of TNFα, but no predisposition for any breast cancer subtype was found, although this polymorphism is associated with an increased risk of metastasis in triple-negative breast cancer." (PMID 33540543, 2021). "In addition, all of the biochemical parameters we analysed were statistically significant in both breast cancer patients (NF-κB: p<0.001; sTRAIL: p<0.01; TNF-α: p<0.001; IL-6: p<0.001; PCT: p<0.001; PTX-3: p<0.001; CRP: p<0.001) and colon cancer patients (for all p<0.001) compared to the control." (PMID 33776564, 2021). "In addition, the positive effects of lifestyle modifications, including physical activity and diets rich in fruits and vegetables, were demonstrated by a clinical trial that revealed decreased TNF-α levels in BRCA1/2+ breast cancer survivors following a yearlong lifestyle modification program." (PMID 34950252, 2021). "It was previously reported in a clinical trial that breast cancer patients may enjoy a good prognosis by reducing the serum levels of inflammatory factors IL-6, IL-8, and TNF-α, and this might even offer protection from the metastases and recurrence of breast cancer." (PMID 34485118, 2021). "Thus, anti-TNFα therapies could be an interesting therapeutic for bone metastatic breast cancer patients." (PMID 33445695, 2021). "However, certain breast cancer patients display resistance to TNF-α responses." (PMID 33816268, 2021). "Importantly, overexpression of A20 not only protects luminal breast cancer cell lines from TNFα-induced cell death via induction of HSP70-mediated anti-apoptotic pathway but also promotes a robust EMT phenotype and metastases by activating the pSTAT3-mediated inflammatory signaling." (PMID 34943954, 2021). "However, it is unclear whether TNF-α is able to induce IP-10 expression in MCF-7 breast cancer cells." (PMID 34572567, 2021). "Finally, our hypothesis was supported by significant adhesion of flow-stimulated breast cancer cells to TNF-α stimulated endothelial cells in static and laminar flow adhesion assays." (PMID 34641959, 2021). "In line with this hypothesis, a recent genetic-based kinome screening against ferroptosis in MDA-MB-231 breast cancer cells, revealed an important role for Syk and other TNFα/NF-κB kinase players suggesting that Syk-mediated inhibition by ferroptotic-inducing agents might be a universal phenomenon." (PMID 34884535, 2021). "The results showed that the secretion of TNF-α, IL-6 and IL-1β were all decreased after AT-I treatment, and we concluded that AT-I could suppress tumorigenesis in breast cancer via inhibiting TLR4/NF-κB pathway, and down-regulate downstream pro-inflammatory cytokines." (PMID 33363472, 2020). "The main limitation of our study is small sample size which could not detect the susceptibility of TNF-α-308G/A polymorphism in each subtypes of breast cancer." (PMID 32102503, 2020).